ATXN2 (ataxin 2)
Diseases named in the same sentence as ATXN2 in open-access papers (continued):
Sharing a sentence is not in itself a finding about the gene and the disease.
amyotrophic lateral sclerosis (continued). "For instance, the Phase 1/2 ALSpire trial (NCT04494256) assessed BIIB105, an investigational ASO designed to reduce ataxin-2 protein levels and mitigate TDP-43 protein aggregation in Amyotrophic Lateral Sclerosis (ALS)." (PMID 40427711, 2025). "Using an exome sequencing approach with ExpansionHunter, we investigated a Norwegian amyotrophic lateral sclerosis cohort for repeat expansions in AR, ATXN1, ATXN2 and HTT." (PMID 38585669, 2024). "Our findings are relevant for ongoing clinical trials that recruit amyotrophic lateral sclerosis patients with repeat expansions in ATXN2 (Clinical Trial NCT04494256), where a drug that reduces the level of ataxin-2 protein is under investigation." (PMID 38585669, 2024). "ATXN2 CAG repeat expansion and the presence of TDP-43 positive neuronal cytoplasmic inclusion bodies are shared molecular characteristics of both SCA2 and amyotrophic lateral sclerosis (ALS)." (PMID 39039334, 2024). "Alleles of ≥31 CAG repeats have also been shown to be risk alleles for amyotrophic lateral sclerosis with or without frontotemporal dementia, suggesting ATXN2 pathogenic mechanisms are complex and dynamic, and that other variants or genes may be implicated in the variable pathogenesis." (PMID 38239855, 2023). "In amyotrophic lateral sclerosis (ALS), ATXN2 is identified as a dose-sensitive modulator of TDP-43 toxicity; the complex formed by these two proteins is mislocalized in spinal cord neurons and eventually leads to ALS." (PMID 34995801, 2022). "In mouse models of Amyotrophic Lateral Sclerosis via TDP-43 overexpression, depletion of its ortholog ATXN2 mitigated motor neuron degeneration and extended lifespan from 25 days to >300 days." (PMID 32698485, 2020). "Five amyotrophic lateral sclerosis patients (1.2%) and two controls (0.3%) carried ≥36 repeats in HTT (P = 0.032), and seven amyotrophic lateral sclerosis patients (1.7%) and three controls (0.4%) carried ≥29 repeats in ATXN2 (P = 0.038)." (PMID 38585669, 2024). "Norwegian amyotrophic lateral sclerosis patients (n = 414) and neurologically healthy controls adjusted for age and gender (n = 713) were investigated for repeat expansions in AR, ATXN1, ATXN2 and HTT using short read exome sequencing and the ExpansionHunter software." (PMID 38585669, 2024). "Mutations in the RBPs, TAR DNA (TARDBP), FUS RNA-binding protein (FUS), Ataxin 2 (ATXN2) as well as EWS RNA-binding proteins (EWSR1) and many more have been shown to greatly influence disease risks, e.g., amyotrophic lateral sclerosis (ALS) and frontotemporal dementia (FDT)." (PMID 35202165, 2022). "Interestingly, in cytoplasmic aggregates, Ataxin-2 intermediate-length polyglutamine has been shown to interact with TDP-43, a nuclear RBP mislocalized in the cytoplasm in amyotrophic lateral sclerosis and other neurodegenerative diseases." (PMID 35053321, 2022). "Ataxin-2 (ATXN2) is a protein conserved across eukaryotic organisms, that in humans is a genetic determinant of at least two neurodegenerative diseases, spinocerebellar ataxia type II (SCA2) and the amyotrophic lateral sclerosis (ALS)." (PMID 33802796, 2021). "Interestingly, the intermediate, non-penetrative expansion size in ATXN2 has been associated with other diseases, specifically amyotrophic lateral sclerosis (ALS) and frontotemporal dementia (FTD)." (PMID 34829728, 2021).
spinocerebellar ataxia (64 papers, 2007 to 2025). "The father of the case was diagnosed with SCA2, an hereditary neurodegenerative disease characterized by progressive cerebellar ataxia caused by abnormal expansion of the cytosine-adenine-guanine (CAG) repeat in the ATXN2 gene." (PMID 39273702, 2024). "Two siblings of Guyanese ancestry who developed ataxia, parkinsonian symptoms and dementia were identified carrying both an expanded allele of C9orf72 and ATXN2 (37/22 repeats)." (PMID 38254109, 2024). "Antisense oligonucleotides targeting ATXN2 was a potential therapy for spinocerebellar ataxia, whose pathogenic mechanism associates with the BDNF expression reduction." (PMID 37072935, 2023). "Antisense oligonucleotides (ASOs) targeting ATXN2 was a potential therapy for spinocerebellar ataxia, whose pathogenic mechanism associates with reduced BDNF expression." (PMID 37072935, 2023). "For instance, an autosomal dominantly-inherited, abnormally long (>33 CAG repeats) trinucleotide repeat expansion within ATXN-2 results in SCA2 that can manifest with ataxia, loss of neurological reflexes, and Parkinsonian symptoms." (PMID 36408113, 2022). "Similar findings were observed for Ataxin-2 (ATX-2), a conserved RNA-binding protein associated with spinocerebellar ataxia in humans, which associates with SZY-20." (PMID 34805187, 2021). "Since another spinocerebellar ataxia repeat in ATXN2 is associated with ALS, this locus is of interest." (PMID 33413375, 2021). "A gene involved in cerebellar ataxia, ATXN2, has also been described as a risk gene for sporadic ALS." (PMID 32968195, 2020). "Cerebellar ataxias and corticospinal motor neuron degeneration are determined by gain/loss in ATXN2 function, so we aimed to identify key molecules in this atrophic process, as potential disease progression markers." (PMID 32932600, 2020). "Polymorphisms in ATXN2 have been associated with multiple neurodegenerative diseases, including spinocerebellar ataxia and Parkinson's disease." (PMID 24586183, 2014). "RBFOX1 physically interacts with the c-terminus of ATXN2, another autosomal dominant gene causing cerebellar ataxia." (PMID 23028291, 2012). "The authors briefly summarized the characteristics of the main types of ataxia and the relationship between ataxin-2 and RNA+ virus infections and suggested that loss of biological function in patients could protect them against infections." (PMID 37754054, 2023). "Long polyglutamine (polyQ) repeats (CAG trinucleotide repeat expansions) in the ataxin-2 (ATXN2) gene may cause spinocerebellar ataxia, but intermediate polyQ repeats (27 to 33 CAG trinucleotide repeat expansions) have been associated with sporadic ALS." (PMID 35563214, 2022). "While human Ataxin-2 and its poly Q stretch have been implicated in spinocerebellar ataxia, it remains largely unknown how this RNA-binding protein is linked to human diseases." (PMID 27689799, 2016). "The functional interactions between Ataxin-1 and Ataxin-2 described here mechanistically tie these two proteins and point to previously unknown pathogenic links between two inherited ataxias." (PMID 18166084, 2007). "Many forms of spinocerebellar ataxia, which are among the most common hereditary ataxias, are caused by trinucleotide repeat expansions in several genes (FXN, ATXN1, ATXN2, ATXN3)." (PMID 41010014, 2025). "Repeat expansions, such as those in HTT (CAG repeats in Huntington’s disease), ATXN1 and ATXN2 (CAG repeats in spinocerebellar ataxias), and FXN (GAA repeats in Friedreich’s ataxia), are well-established causes of neurodegenerative disorders." (PMID 40166539, 2025). "Studies have shown that intermediate STR expansions in the spinocerebellar ataxia (SCA) genes, ATXN1 (SCA1) and ATXN2 (SCA2) are associated with ALS risk." (PMID 40012994, 2025).
spinocerebellar ataxia (continued). "This study involved six genes (ATXN1, ATXN3, ATXN7, HTT, NOP56, and PPP2R2B), while a higher detection rate has been reported in a spinocerebellar ataxia cohort (4.4%, 22/498), which included five genes (ATXN2, ATXN3, NOP56, AR and HTT)." (PMID 38308084, 2024). "Genetic testing on an ataxia panel identified a CAG repeat size in ATXN2 of 32 and 22 repeats, confirmed on repeat testing." (PMID 35192242, 2022). "Evidence of the possible molecular action of 17-DMAG on ATXN2 expression came from another spinocerebellar ataxia study, on SCA3." (PMID 35787375, 2022). "In vitro experiments showed that the ELF2 mutation led to an increased expression of Ataxin-2 (SCA2) as well as a reduced expression of ELOVL5 (SCA38), a result establishing links between ELF2-disorder and other ataxia subtypes." (PMID 38835435, 2021). "The ATXN2 CpG island has been studied in the context of spinocerebellar ataxias (SCAs) and differences in the disease course of SCA2 patients correlated with the different methylation level of the ATXN2 promoter." (PMID 32630630, 2020). "Spinocerebellar ataxia (SCA) type 2 and 3 are caused by cytosine–adenine–guanine (CAG)n repeat expansions in ATXN2 and ATXN3 genes (OMIM 601517, 607047), which are the most common types of SCAs in China." (PMID 30920184, 2019). "The Pbp1 protein is homologous to human ataxin 2 (ATXN2), which itself causes spinocerebellar ataxia when its polyglutamine tract is expanded from a typical length of ~22 to >34." (PMID 30618605, 2018). "Our present findings clarify the position of ATXN2 effects in the emerging shared molecular pathways of spinocerebellar ataxias." (PMID 26868665, 2017). "Mutations in other putative RNA binding proteins, such as FUS, ataxin-2, SMN and FMRP, are associated with familial ALS, spinocerebellar ataxia, spinal muscular atrophy and fragile X syndrome, respectively." (PMID 20948999, 2010). "SCA1 and SCA2 are two ataxias caused by expansion of polyglutamine tracts in Ataxin-1 (ATXN1) and Ataxin-2 (ATXN2), respectively, two proteins that are otherwise unrelated." (PMID 18166084, 2007). "Expansions over 34 CAG repeats in ATXN2 gene are linked to adult-onset SCA2, a severe neurodegenerative condition characterized by progressive cerebellar ataxia, saccadic slowing, extrapyramidal movement disorder (e.g., parkinsonism and myoclonus), and subsequent brainstem involvement." (PMID 40002489, 2025). "Current clinical trials use ataxia scores, cerebellar imaging, nerve conductance, perhaps the quantitation of NfL as axonal damage marker, and ATXN2 to assess efficacy of disease protein elimination, but molecular biomarkers in the affected pathways are lacking." (PMID 41298695, 2025). "In this regard, genetic causes could have a significant role considering the recent observation that genetic risk alleles for ALS also include spinocerebellar ataxia-associated genes (i.e., ATXN1, ATXN2)." (PMID 36370302, 2023). "This is interesting because ATXN2 polyQ repeats cause autosomal dominant SCA2 (≥ 33 repeats) or increase ALS risk (31–32 repeats) through neuronal ATXN2 aggregation and the affected individuals show both progressive ataxia and muscle weakness and atrophy." (PMID 36136249, 2022). "Spinocerebellar ataxia (SCA-2) type-2 is a rare neurological disorder among the nine polyglutamine disorders, mainly caused by polyQ (CAG) trinucleotide repeats expansion within gene coding ataxin-2 protein." (PMID 28119557, 2016). "In addition, SPG11 and FUS can be sequenced in cases who also present mental retardation, while SOD1, Alsin, SETX, ATXN2 can be considered in those cases with coexistence of cerebellar ataxia." (PMID 26843957, 2016). "Coexistence with cerebellar ataxia may suggest the involvement of mutations of SOD1, ATXN2, Alsin, and SETX." (PMID 26213621, 2015).
spinocerebellar ataxia (continued). "We also showed that multiple ATXN2-associated phenotypes can be present within the same pedigree or even the same patient, including ALS, parkinsonism and perhaps even ET, although it is difficult to exclude the possibility that the latter was a mild form of SCA2 presenting with subtle ataxia." (PMID 39956874, 2025). "Thus neuronal degeneration may take place through common mechanisms in different ataxias, and one of these mechanisms may involve the abnormal accumulation of Ataxin-2 in neuronal nuclei." (PMID 18166084, 2007). "The frequency is followed by ATXN7: 6.09%, TBP: 5.59%, ATXN2: 5.03%, CACNA1A: 4.28%, PPP2R2B: 2.68%, and ATXN3: 2.42% with respective cutoff values in uncharacterized ataxia cases." (PMID 36618024, 2022). "Uninterrupted CAG repeat expansions in ATXN2 (34 and greater) present with SCA2, which is characterized by cerebellar dysfunction and ataxia." (PMID 34077532, 2021). "This work supports that ELF2 gene regulates the expression of ATXN2 and ELOVL5 genes, and defines new molecular links in the pathophysiology of cerebellar ataxias." (PMID 29628936, 2018). "For instance, non-pathogenic alleles of the spinocerebellar ataxia-related genes ATXN1 (SCA1; OMIM 164400) and ATXN2 (SCA2; OMIM 183090) have tracts interrupted by 1–3 CAT (His) codons in ATXN1 and CAA (Gln) codons in ATXN2." (PMID 39125760, 2024). "Using WGS data, the Expansion Hunter tool predicted a repeat expansion of ATXN2 exon 1 CAG microsatellite, which was prioritized due to the clear association to cerebellar ataxia, and a lack of other clear causative variants." (PMID 38239855, 2023). "In addition to cerebellar ataxia, motor neuron disease is often seen in SCA2, and ATXN2 CAG repeat expansions in the long normal range increase ALS risk." (PMID 32307524, 2020). "Indeed, recent screens in S. cerevisiae, C. elegans and D. melanogaster documented a role for ATXN2 as a generic modifier that affects multiple if not all neurodegenerative diseases, including several polyQ-triggered spinocerebellar ataxias." (PMID 25721894, 2015). "However, we have termed a subset of ataxias, not just with reduced IP3R1 but also with supersensitive IP3R1, and regardless of the mutated gene (e.g., ITPR1, Ataxin-1, Ataxin-2, Ataxin-3) as ‘IP3R1-associated ataxias’." (PMID 22703638, 2012). "Treatment with dasatinib, a clinically approved Src inhibitor, improved PC spontaneous firing in the acute cerebellar slice and delayed ataxia progression in mice lacking MTSS1 and in ATXN2[Q127] mice." (PMID 39872677, 2025). "Given that ATXN2 and ATXN7 have not been described to act through Cic, it is tempting to speculate that the ion channel module we have identified represents an important shared pathway for Purkinje neuron pathology in many spinocerebellar ataxias." (PMID 32964235, 2020).
Parkinsonism (49 papers, 2009 to 2025). Characteristic neurologic anomaly resulting from degeneration of dopamine-generating cells in the substantia nigra, a region of the midbrain, characterized clinically by shaking, rigidity, slowness of movement and difficulty with walking and gait. "The long ATXN1 allele and the CAG size and both the short and long alleles of ATXN2 were predictor variables of the Parkinson’s disease risk." (PMID 39974178, 2025). "The long ATXN1 and HTT alleles and CAG size and both the ATXN2 short and long alleles were predictors for the Parkinson’s disease risk." (PMID 39974178, 2025). "In mouse models of SCA2, this approach has been shown to significantly reduce ATXN2 mRNA and protein levels and attenuate electrophysiological abnormalities。Parkin mutations are associated with most familial early-onset Parkinson's disease." (PMID 39039334, 2024). "We described an association of HTT, ATXN1 and ATXN2 with the risk of Parkinson’s disease, which reinforce the hypothesis of the common pathway of neurodegeneration." (PMID 39974178, 2025). "The best logistic model for prediction of Parkinson’s disease risk in reference to the ATXN2 CAG repeats (P = 1.68–06; AIC = 2037) included as predictors the quadratic term of the short allele (P = 2.72e−04), the long allele (P = 0.002) and the interaction between both alleles (P = 0.002)." (PMID 39974178, 2025). "Significant expansion of this tract (greater than 34 CAG repeats) is the genetic cause of spinocerebellar ataxia 2 (SCA2), intermediate expansions of the ATXN2 polyQ tract have been associated with parkinsonism, and some ATXN2 polyQ expansions have been associated with ALS." (PMID 39200113, 2024). "These critical findings established the importance of ATXN2 as a common contributor to ALS and provided yet another example of proteins misfolding across multiple neurodegenerative disorders, as ATXN2 can also contribute to Parkinson’s disease and mutations in ATXN2 cause SCA2." (PMID 30425620, 2018). "Molecular mechanisms underlying parkinsonism caused by ATXN2 expansions are still unclear." (PMID 28955296, 2017). "The molecular mechanisms underlying Parkinsonism caused by ATXN2 expansion remain unclear." (PMID 31725623, 2019). "We conclude that CAG-repeat expansions in ATXN2 exhibit pleiotropy and are associated with a disease spectrum that includes ALS, SCA2, and parkinsonism; to recognise this complexity we propose the new term ‘ATXN2-related neurodegeneration’." (PMID 39956874, 2025). "In our study, the proband 1(F1: II-4) with parkinsonism harbored 35 CAG repeats in ATXN2 and developed symptoms at age 37, aligning with these observations." (PMID 41001200, 2025). "This study aimed to investigate the influence of CAG repeat sizes in ATXN1, ATXN2 and HTT genes on the risk for developing cancer and Parkinson’s disease in a large cohort of patients with idiopathic Parkinson’s disease and healthy controls." (PMID 39974178, 2025). "A-syn brain aggregates are the main inclusions found in Parkinson’s disease brains, whereas huntingtin (Htt), ataxin-1 and ataxin-2 are the main components of Huntington disease, SCA1 and SCA2, respectively." (PMID 39974178, 2025). "CAG repeat expansions in the ATXN2 gene have been associated with variable neurological presentations, which include SCA2, ALS, Parkinsonism, or a combination of them." (PMID 38642323, 2024). "Parkin interacts with the terminals of ATXN2 to ubiquitinate normal and extended ATXN2, which together are involved in early-onset Parkinson's disease." (PMID 39039334, 2024). "Initially, researchers observed that the length of poly(Q) repeat amplification in ATXN2 is implicated in the pathogenesis of ALS, SCA2, and Parkinson's disease, and that the sequence encoding the poly(Q) repeat varies across these diseases." (PMID 39039334, 2024). "Some of the genes that were steadily down-regulated, such as Pink1, Park 2, Sv2b, Gabbr2, Sept5 and Atxn2, were directly related to Parkinson’s onset." (PMID 29156651, 2017).